PSTPIP2 (proline-serine-threonine phosphatase interacting protein 2)
Diseases named in the same sentence as PSTPIP2 in open-access papers (continued):
Sharing a sentence is not in itself a finding about the gene and the disease.
viral infections (1 paper, 2023). "ITGAM, RUNX1, and PSTPIP2 formed one cluster with high expression in subjects with confirmed bacterial infections, whereas LY6E and IRF-9 formed another cluster with high expression in patients with confirmed viral infections." (PMID 36900096, 2023). "ITGAM, RUNX1, and PSTPIP2 formed one cluster with high expression in subjects with confirmed bacterial infections, whereas LY6E and IRF-9 formed another cluster with high expression, mainly in patients with confirmed viral infections." (PMID 36900096, 2023).
bacterial infection (3 papers, 2008 to 2024). "uncovered that PSTPIP2 was highly expressed in the confirmed bacterial infection patients, correlating with infection status." (PMID 39654884, 2024).
infection (3 papers, 2019 to 2024). The state of being infected such as from the introduction of a foreign agent such as serum, vaccine, antigenic substance or organism. "Notably, the role of each of the five genes (ITGAM, IRF-9, LY6E, PSTPIP2, and RUNX1) has been linked to response to infection in the literature." (PMID 36900096, 2023). "There were statistically significant associations between positive infection status and four of the five genes: IRF-9 (OR = 1.750, 95% CI = 1.16–2.638), ITGAM (OR = 1.533, 95% CI = 1.047–2.244), PSTPIP2 (OR = 2.191, 95% CI = 1.293–3.711), and RUNX1 (OR = 1.974, 95% CI = 1.069–3.646)." (PMID 36900096, 2023). "IRF-9 (OR = 1.750, 95% CI = 1.16 to 2.638), ITGAM (OR = 1.533, 95% CI = 1.047 to 2.244), PSTPIP2 (OR = 2.191, 95% CI = 1.293 to 3.711), and RUNX1 (OR = 1.974, 95% CI = 1.069 to 3.646) had a significant expression with positive infection status." (PMID 36900096, 2023).
skin- (2 papers, 2023 to 2024). "Regarding CNV analysis, we found that PANoptosis genes, especially NLRP3, RBCK1, PSTPIP2, and TNFAIP3, may promote tumor progression via CNV alteration." (PMID 36890219, 2023).
immune disorders (1 paper, 2024). "While researchers are actively delving into the role of PSTPIP2 in various immune disorders, the precise mechanisms underlying its function in some of these diseases, such as its inhibition of IL-1β, remain incompletely understood." (PMID 39660128, 2024). "PSTPIP2, as a relevant protein, underscores its significance value in immune disease research by suppressing immune responses and mitigating the damage caused by the immune system to the body." (PMID 39660128, 2024).
PSTPIP2 also shares sentences with these, for which no sentence is quoted: atherosclerosis (2 papers); diabetes (2); nephropathy (2); pyoderma gangrenosum (2); synovitis (2); autoinflammatory syndrome (1); chronic granulomatous disease (1); hepatitis C (1); Majeed syndrome (1); osteoarthritis (1); osteopetrosis (1); pneumonia (1); pressure ulcers (1); pyogenic arthritis (1); sarcoidosis (1).